TRAF3 (TNF receptor associated factor 3)
Diseases named in the same sentence as TRAF3 in open-access papers (continued):
Sharing a sentence is not in itself a finding about the gene and the disease.
viral infection (continued). "Similarly, it has been reported that some deubiquitinases including OTUB1/2, UCHL1, MYSM1 and DUBA can remove K63-linked ubiquitination of either TRAF3 or TRAF6, thus inhibiting IFNs production during viral infection." (PMID 29734366, 2018). "However, until this point there are few studies that clearly analyzed the dynamics of downregulation of MAVS/TRAF3/TRAF6 proteins during viral infection." (PMID 29734366, 2018). "However, how viral infection induces some common mechanisms to negatively regulate the stability of MAVS/TRAF3/TRAF6 signalosome remains to be illuminated." (PMID 29734366, 2018). "TRAF3 regulates viral infection-triggered induction of IFNβ." (PMID 29734366, 2018). "The role of Smurf1 in regulating TRAF3/TRAF6 protein levels during viral infection remains unknown so far, although Smurf1 was reported to be able to bind to and ubiquitinate exogenous Myc-TRAFs family members in HEK293T cells." (PMID 29734366, 2018). "Finally, the deubiquitinase OTUD1 potently inhibits RLR pathway by utilizing Smurf1-MAVS/TRAF3/TRAF6 signaling at the early stage of viral infection." (PMID 29734366, 2018). "We next sought to determine how viral infection affects the levels of OTUD1, Smurf1 and MAVS/TRAF3/TRAF6, and whether the regulation signaling of OTUD1-Smurf1-MAVS/TRAF3/TRAF6 occurs during viral infection." (PMID 29734366, 2018). "We found that iOPN interacted with TRAF3 after virus infection." (PMID 27026194, 2016). "After viral infection, HSCARG interacted with tumor necrosis receptor-associated factor 3 (TRAF3) and inhibited its ubiquitination by promoting the recruitment of OTUB1 to TRAF3." (PMID 24763515, 2014). "Compared to the control, MG132 treatment did not change the TRAF3 ubiquitination level, suggesting that TRAF3 barely undergoes K48-linked ubiquitination at 6 h after viral infection." (PMID 24763515, 2014). "Notably, cIAP1 and cIAP2 are also recruited to MAVS, and mediate K48- and K63- linked polyubiquitination of TRAF3 and TRAF6 in response to viral infections." (PMID 23758787, 2013). "For example, upon viral infection, Triad3A is up-regulated, and induces K48-linked ubiquitination and degradation of TRAF3, thereby forming a negative feedback loop to halt RIG-I signaling and type I IFN production." (PMID 23758787, 2013). "However, upon viral infection or transfection with poly I:C or poly dA:dT, immunocomplexes containing endogenous TRAF3 were enriched with p115 and Sec16A." (PMID 22792062, 2012). "Therefore, we next addressed the subcellular localization of endogenous TRAF3 upon viral infection and RNA/DNA sensor pathway activation." (PMID 22792062, 2012). "Thus, we propose that these two trafficking proteins, Sec16A and p115, form a complex with TRAF3 at ER-to-Golgi transport compartments in order to ensure its proper recruitment to the mitochondrial network during a viral infection." (PMID 22792062, 2012). "However, this possible mechanism of action requires further investigation to determine how TRAF3 is recruited to the mitochondrial adaptor protein MAVS upon viral infection." (PMID 22792062, 2012). "Upon virus infection, TANK has been shown to associate with MAVS as well as TRAF3 and TBK1." (PMID 20161788, 2010). "However, genetic disruption of TRAF3 has been shown to only partially inhibit the response to virus infection." (PMID 20161788, 2010). "Triad3A was induced following dsRNA exposure or virus infection and decreased TRAF3 levels in a dose-dependent manner; moreover, Triad3A expression blocked IRF-3 activation by Ser-396 phosphorylation and inhibited the expression of type 1 interferon and antiviral genes." (PMID 19893624, 2009). "In addition, it was determined by time-course analysis that 6h dsRNA treatment and 16h virus infection resulted in maximal TRAF3 degradation." (PMID 19893624, 2009).
viral infection (continued). "The TRAF3-dependent pathway has been genetically confirmed by experiments showing that Traf3−/− MEF cells show impaired production of type I IFNs but normal activation of NF-κB in response to viral infection." (PMID 19479062, 2009). "However, viral infection or cIAP1/2 overexpression did not cause noticeable degradation of TRAF3/6, and activation of downstream kinases such as TBK1 and TAK1 were proposed." (PMID 27716849, 2016). "However, the relationship between RIP-1 and the TRIF/TRAF1, TRAF2, and TRAF3 pathways to produce cytokines after viral infection is unknown." (PMID 25754842, 2015). "The phosphorylation of TRAF3 by CK1 ε led to the recruitment of another kinase called TBK1 to TRAF3, suggesting that CK1 plays a significant role in regulating the innate immune response to viral infections and provides a novel mechanism of immunoregulation." (PMID 38023245, 2023). "qRT-PCR analyzed the immune genes, including IL-1β, TRAF3, TNF-α, and TLR2 expression levels in JFSP cells after virus infection." (PMID 36552207, 2022). "For instance, OTUD1 increases Smurf1 expression levels to promote degradation of the MAVS/TRAF3/TRAF6 signalosome and inhibit the innate immune response to viral infection." (PMID 35280681, 2022). "In response to viral infection, TRAF3IP3 bridges TRAF3 and MAVS leading to interferon production, indicating it’s probably strong relationship with Covid-19 disease." (PMID 35694544, 2022). "To this end, we examined the ability of TRAF3 to interact with both MAVS and TBK1 upon viral infection in HEK293T cells in which endogenous TFG was knocked down with a TFG-specific short interfering RNA (siRNA, siTFG)." (PMID 33411856, 2021). "Our results detail the functional role of TFG in innate immunity as an ER-to-Golgi resident protein which allows TRAF3 to interact with upstream adapter protein MAVS and downstream kinase TBK1 resulting in activation of TBK1 upon viral infection." (PMID 33411856, 2021). "Upon viral infection, together with TBK1, TRAF3 transits from the perinuclear region onto MAVS-containing supramolecular complexes and promotes signaling events leading to TBK1 activation." (PMID 33411856, 2021). "We identify TFG as being part of a molecular complex comprised of at least MAVS, TRAF3 and TBK1 and requirement of TFG in the interactions of TRAF3 with TBK1 and MAVS upon viral infection." (PMID 33411856, 2021). "Here, we present the crosstalk of mTOR and RLR-signaling pathways by demonstrating the requirement of TFG for the interaction of TRAF3 and TBK1 with mTOR upon viral infection." (PMID 33411856, 2021). "The co-IP assay performed with HEK293T cells that were transfected with plasmids to express TRAF3-Flag and then infected with WSN (H1N1) virus, revealed the interaction between PB2 and TRAF3 during the viral infection course." (PMID 32562145, 2020). "TRAF3 binds to a functional site in the proline-rich region of VISA, which is critical for IFN production upon viral infection." (PMID 32562145, 2020). "For example, USP25 was reported to be able to enhance the stability of TRAF3 and TRAF6, thus promoting IFNs induction by viral infection." (PMID 29734366, 2018). "These deubiquitinases can be activated during viral infection, and then stabilize MAVS, or TRAF3, or TRAF6 protein, which finally promotes IFNs production and host antiviral defense." (PMID 29734366, 2018). "However, it was reported that in TRAF3-deficient MEFs RNA viruses can normally activate IRF3 and induce a modestly reduced level of IFNβ, suggesting that the function of TRAF3 can be substituted by other antiviral signaling for IFNs induction during viral infection." (PMID 29734366, 2018). "Third, RNF166 interacted with endogenous TRAF3 and TRAF6, and these interactions were enhanced upon viral infection." (PMID 26456228, 2015). "The E3 ligase TRAF3 plays a critical role in Toll-dependent and independent induction of IFN-β in response to virus infection." (PMID 23308279, 2013).
viral infection (continued). "It is of paramount importance to emphasize that TRAF3 is meticulously regulated during viral infections, a phenomenon that is not unexpected given its pivotal role in this process." (PMID 39058724, 2024). "TRAF3 expression was significantly elevated at both mRNA and protein levels in VACV-specific eEF-2K−/− effector CD8+ T cells, which is consistent with its known role in promoting type I interferon responses during viral infections." (PMID 39861816, 2024). "In addition, the expression of four immune-related genes, TRAF3, IL-1β, TNF-α, and TLR2, was differentially altered following viral infection." (PMID 36552207, 2022). "Viral infection experiments demonstrated that the IAV WT virus, but not NS1 E152A/153A virus, effectively suppressed the K63-linked ubiquitination of TRAF3 induced by RIG-I-CARD and MAVS respectively." (PMID 34610835, 2021). "Since BIRC2/BIRC3 and TRAF2/3 could form a cytoplasmic complex, where BIRC2/BIRC3 mediated ubiquitination and degradation of TRAF3, the roles of BIRC2/BIRC3 in viral infection were extensively investigated." (PMID 34887869, 2021). "TRAF3 is known as a central mediator of type I interferon (IFN) induction by various pattern recognition receptors, but the in vivo function of TRAF3 in host defense against viral infection is poorly defined due to the lack of a viable mouse model." (PMID 30622699, 2019). "Here, our results indicate that OTUD1 could utilize Smurf1 to downregulate MAVS/TRAF3/TRAF6 proteins and restrict IFNs production during viral infection." (PMID 29734366, 2018). "Therefore, we think that at the late stage of viral infection, more signaling molecules take part in the regulation of the MAVS/TRAF3/TRAF6 signalosome, and finally result in the right balance of RLR-MAVS-IFNs signaling." (PMID 29734366, 2018). "Our data suggest that FOSL1 interacts with TRAF3 and TRIF in immune cells after viral infection." (PMID 28049150, 2017). "We were able to detect significant amounts of MAVS interacting with TRAF3 in the cells treated with control shRNA, upon SeV infection but not in the absence of viral infection." (PMID 28848563, 2017). "We first screened the reported deubiquitinases for TRAF3 and found that HSCARG interacted with OTUB1 more potently than OTUB2, UCHL1, OTUD7B, and USP25, and this interaction was enhanced by viral infection." (PMID 24763515, 2014). "Using similar approaches, we also show that TRAF, but not TRAF-3, is involved in activation of Rel2 after viral infection." (PMID 24762775, 2014). "On the other hand, the interaction between WDR77 and TRAF3 was not influenced by virus infection." (PMID 37563140, 2023). "Given that MAVS is a mitochondrial protein and Smurf1 can regulate MAVS/TRAF3/TRAF6 proteins during RNA virus infection, we speculate that upregulated Smurf1 proteins by viral infection could be able to localize to the mitochondria to interact with the MAVS/TRAF3/TRAF6 signalosome." (PMID 29734366, 2018). "However, TRAF3 was demonstrated to link the mitochondrial membrane-bound protein MAVS to the activation of TBK1, which is required for IRF3/7 phosphorylation and type I IFN induction in response to viral infection." (PMID 22792062, 2012). "Moreover, consistent with previous reports showing the recruitment of TRAF3 to MAVS as an important process leading to downstream signaling, the silencing of TFG also blunted the activating transautophosphorylation of TBK1 on Ser172 (p-TBK1 Ser172) normally observed upon viral infection." (PMID 33411856, 2021). "However, how TRAF3 reacts in response to a viral infection is still not totally understood." (PMID 22792062, 2012). "In this study, we observed the TLR3/TRIF/RIP-1 pathway also involved in TRAF1, TRAF2 and TRAF3 activation, but not TRAF6 after stimulation by dsRNA or viral infection in the corneal epithelium." (PMID 25754842, 2015).
multiple myeloma (40 papers, 2010 to 2025). "Aberrant B cell expansion and survival contribute to B cell malignancies, such as multiple myeloma, diffuse large B cell lymphoma, and chronic lymphocytic leukemia, which are frequently associated with TRAF3 gene deletions or inactivating mutations." (PMID 40821837, 2025). "TRAF3 gene deletion or loss of function was identified in tumor cells from patients with multiple myeloma, preventing the binding of TRAF3 and NIK." (PMID 36845015, 2023). "Reinforcing the evidence obtained from mouse models, somatic mutations (such as homozygous deletions and inactivating mutations) of the TRAF3 gene in humans were first identified in multiple myeloma (MM) and then other B cell malignancies." (PMID 36776285, 2023). "Consistent with the importance of TRAF3 in B cell biology, deletions and inactivating mutations of the TRAF3 gene were first reported in human multiple myeloma (MM), a malignancy derived from plasma cells." (PMID 36776285, 2023). "Mutations that inhibit the function of TRAF3 lead to constitutively active NF-κB in patients with multiple myeloma." (PMID 32514408, 2020). "TRAF3 has a major immunomodulatory function and TRAF3 deficiency has been linked to malignancies, such as multiple myeloma and lymphoid defects." (PMID 32514408, 2020). "B cell-specific TRAF3 deficiency results in enhanced viability and is associated with development of lymphoma and multiple myeloma." (PMID 27752131, 2016). "A TRAF3 deficient MC1286.PE3 MMCL was generated from primary myeloma MC1286 cells during a subsequent relapse." (PMID 24980832, 2014). "Single nucleotide polymorphisms (SNPs) of TRAF3 are also associated with altered risk of multiple myeloma." (PMID 23758787, 2013). "Recently, constitutive activation of NIK – by direct mutation or mutation of its negative regulators cIAP1/2 and TRAF3 – has been identified in multiple myeloma." (PMID 21151480, 2010). "However, although Traf3 has been described as a tumor suppressor and loss of Traf3 was found in a subset of multiple myeloma patients, increased levels of TRAF3 in Traf3 transgenic mice also promoted autoimmunity, inflammation, and cancer." (PMID 30262843, 2019). "The TRAF3 gene is also significantly mutated in multiple myeloma." (PMID 26377837, 2015). "Deletions and mutations of TRAF3 have been reported in multiple myeloma, Waldenström’s macroglobulinemia, Hodgkin lymphomas (HLs), and a variety of non-Hodgkin lymphomas (NHLs), including splenic marginal zone lymphoma, B cell chronic lymphocytic leukemia (B-CLL), and mantle cell lymphoma." (PMID 23758787, 2013). "Reconstitution of TRAF3 in human multiple myeloma cell lines inhibited ChoKα expression, suppressed the Kennedy pathway, and induced apoptosis, underscoring the role of elevated choline metabolism in sustaining the phenotype of TRAF3-deficient malignant B cells." (PMID 40821837, 2025). "Corroborating our findings, TRAF3 deletions and inactivating mutations frequently occur in human B cell chronic lymphocytic leukemia, splenic marginal zone lymphoma, mantle cell lymphoma, multiple myeloma, Waldenström’s macroglobulinemia, and Hodgkin lymphoma." (PMID 25960828, 2015). "Further autophagic degradation of TNF receptor associated factor (TRAF3), a key step in osteoclast differentiation, was inhibited by eliglustat, evidenced by TRAF3 action in restoring osteoclast formation in bone marrow cells in myeloma." (PMID 40869407, 2025). "Gene expression studies performed by Kuehl and colleagues showed that multiple myeloma is associated explicitly with TRAF2 and TRAF3 gene mutations that promote activation of the NFκB system via an alternative pathway." (PMID 39061149, 2024). "Research has indicated that TRAF3 plays an active role in inflammation-related diseases such as multiple myeloma, systemic lupus erythematosus, and herpes simplex encephalitis." (PMID 38018974, 2024).
multiple myeloma (continued). "In a recent proteomic study, we identified the key mitochondrial fission factor, MFF, as a new interacting protein of TRAF3, a known tumor suppressor of multiple myeloma and other B cell malignancies." (PMID 36776285, 2023). "Here, the authors show that the glycosylceramide synthesis inhibitor and FDA approved drug Eliglustat inhibits autophagic degradation of TRAF3 which is a key step for osteoclast differentiation and thereby improves myeloma bone lesions." (PMID 36550101, 2022). "Eliglustat blocked autophagy by altering glycosphingolipid composition whilst restoration of missing glycosphingolipids rescued autophagy markers and TRAF3 degradation thus restoring osteoclastogenesis in bone marrow cells from myeloma patients." (PMID 36550101, 2022). "The NFκB pathway was altered in 45% of HMCLs, mostly by inactivating TRAF3 (frame-shift, non-sense mutation, insertion or deletion) or BIRC2/BIRC3 (homozygous deletion) as previously reported in primary myeloma cells." (PMID 30545397, 2018). "Regardless of the mechanism, NGS findings suggest a clonal relationship with clonal evolution and a possible role of NF1, TNFAIP3 and TRAF3 in myeloid transformation of plasma cell myeloma." (PMID 29463311, 2018). "Here we discuss our new translational data that demonstrate the therapeutic potential of targeting TRAF3 downstream signaling pathways in B lymphoma and multiple myeloma." (PMID 25960828, 2015). "In particular, mutations in NF-κB inducing kinase (NIK), TRAF3, TRAF2, and cellular inhibitors of apoptosis 1 and 2 (cIAP1, cIAP2) are highly associated with human multiple myeloma (MM) and MM-derived cell lines." (PMID 24391649, 2013). "Recent studies of mutations in multiple myelomas revealed that NIK, or more frequently proteins such as TRAF3 and cIAPs that control NIK degradation, are targets for mutation in these tumors." (PMID 21151480, 2010). "This gene, along with others such as TRAF3, are known to regulate NF-κB signaling in myeloma." (PMID 40453054, 2024). "Mutations leading to constitutive activation of the kinase NIK in multiple myeloma have been found in NIK itself, that disrupts its binding with TRAF3, in turn causing dissociation of NIK from the inhibitory complex having TRAF2 and the ubiquitin ligases cIAP1 and cIAP2." (PMID 36899924, 2023). "Interestingly, some multiple myelomas have small deletions of NIK, which prevent NIK from binding to TRAF3 and increase its stability consistent with the findings of TRAF3 mutation." (PMID 36845015, 2023). "This work delineates both the mechanism by which glucosylceramide synthase inhibition prevents autophagic degradation of TRAF3 to reduce osteoclastogenesis as well as highlighting the clinical translational potential of eliglustat for the treatment of myeloma bone disease." (PMID 36550101, 2022). "TRAF3 was recently identified as a tumor suppressor in human multiple myeloma." (PMID 32579175, 2020). "The analysis of TRAFs or cIAPs mutant multiple myeloma and cIAPs- or TRAFs-deficient MEFs demonstrated that NIK degradation is ensured by the TRAF3-TRAF2-cIAP1 ubiquitin ligase complex, in which TRAF3 serves as NIK-binding component and recruits cIAPs via TRAF2." (PMID 32365919, 2020). "These novel driver mutations hit histone proteins (HIST1H1D; HIST1HIC) involved in resistance to lenalidomide in multiple myeloma (IKZF3), nuclear RNA export factor 1 (NXF1) and proteins also mutated in acute myeloid leukemia and multiple myeloma (ASXL1; TRAF3)." (PMID 27580852, 2016). "Furthermore, frequent homozygous deletions of genes playing important role in myeloma biology such as TRAF3, BIRC1/BIRC2, RB1, or CDKN2C were observed." (PMID 24987674, 2014). "In approximately 20% of multiple myeloma cases loss-of-function mutations for TRAF2, TRAF3 and cIAP1/2 have been identified in patients, leading to NIK-induced activation of both the canonical and alternative NF-κB pathways to regulate cell growth and survival." (PMID 23301098, 2013).